SGSH (N-sulfoglucosamine sulfohydrolase)
Description:
Catalyzes a step in lysosomal heparan sulfate degradation.
Synonyms: HSS; MPS3A; SFMD
Tractability: Antibody: UniProt predicts a signal peptide or a membrane-spanning region. PROTAC: ubiquitination databases record sites on it; its protein half-life has been measured.
Gene: Protein-coding gene on chromosome 17 (80,206,716 to 80,220,923, reverse strand). Ensembl gene ENSG00000181523.
Subcellular location: Lysosome
Pathways (Reactome):
Disease: MPS IIIA - Sanfilippo syndrome A
Metabolism: HS-GAG degradation
Gene Ontology:
Molecular function: N-sulfoglucosamine sulfohydrolase activity; protein binding; sulfuric ester hydrolase activity
Biological process: glycosaminoglycan catabolic process; heparan sulfate proteoglycan catabolic process
Cellular component: extracellular exosome; lysosome; lysosomal lumen
Genetic constraint (gnomAD): Loss-of-function variants: 48 observed, 48.46 expected, observed/expected ratio (o/e) 0.99, 90% interval 0.79 to 1.26. The upper end of that interval is the gene's LOEUF score, 1.26, which puts it in group 5 of 6, group 1 being the genes least tolerant of losing a copy. Missense variants: 662 observed, 704.21 expected, observed/expected ratio (o/e) 0.94, 90% interval 0.88 to 1. Synonymous variants: 321 observed, 306.78 expected, observed/expected ratio (o/e) 1.05, 90% interval 0.95 to 1.15.
Gene-disease validity (ClinGen):
ClinGen rates the evidence that SGSH causes each of these diseases.
mucopolysaccharidosis type 3A (autosomal recessive): Definitive. A rare autosomal recessive lysosomal storage disease caused by deficiency of the enzyme heparan sulfate sulfatase.
Homologues: Orthologues: chimpanzee SGSH (99% identical), macaque SGSH (96% identical), guinea pig SGSH (91% identical), dog SGSH (90% identical), mouse Sgsh (89% identical), rat Sgsh (88% identical), pig SGSH (88% identical), tropical clawed frog sgsh (73% identical), zebrafish sgsh (71% identical), Drosophila melanogaster Sgsh (54% identical), rabbit SGSH (50% identical). Paralogues in human: ARSA (26% identical), GALNS (26% identical), ARSL (26% identical), ARSF (25% identical), ARSH (24% identical), STS (24% identical), ARSG (24% identical), ARSD (23% identical), ARSB (22% identical), ARSI (21% identical), ARSJ (20% identical), GNS (20% identical), and 4 more.
Diseases named in the same sentence as SGSH in open-access papers:
SGSH is named in the same sentence as 37 diseases in open-access papers, as found by Europe PMC text mining. Sharing a sentence is not in itself a finding about the gene and the disease. The quoted sentences say what the papers report.
Mucopolysaccharidosis type IIIA (17 papers, 2011 to 2026). "The present study aims to identify the SGSH mutational spectrum in a cohort of Egyptian children patients with Sanfilippo Syndrome type A, who were ascertained based on the results of the biochemical enzyme deficiency." (PMID 40855326, 2025). "SGSH mutations are responsible for mucopolysaccharidosis type IIIA, the most common form of Sanfilippo syndrome, an autosomal recessive disorder of lysosome storage with onset in childhood." (PMID 38592608, 2024). "For example, the heterozygous c.220C>T mutation was detected in the SGSH gene causing mucopolysaccharidosis type 3A (Sanfilippo A)." (PMID 30548430, 2019). "The structure also provides insight into the diverse effects of pathogenic mutations on SGSH function in mucopolysaccharidosis type IIIA and convincing evidence for the molecular consequences of many missense mutations." (PMID 24816101, 2014). "Mucopolysaccharidosis (MPS) IIIA, also known as Sanfilippo syndrome type A, is a neurodegenerative lysosomal storage disorder caused by a deficiency in the enzyme N-sulfoglucosamine sulfohydrolase (SGSH, EC:3.10.1.1), which is involved in the degradation of heparan sulfate." (PMID 31385193, 2019). "Exome sequencing (NimbleGen SeqCap V2, Roche, Mannheim, Germany) followed by Illumina GAIIx paired-end sequencing for 2×76bp (Illumina, San Diego, CA, USA) uncovered a homozygous mutation c.416C > T, p.T139M in the SGSH gene causing mucopolysaccharidosis type IIIA, that is, Sanfilippo A syndrome." (PMID 24576347, 2014). "Mucopolysaccharidosis type IIIA (MPS-IIIA) is a form of Sanfilippo syndrome resulting from a deficiency in functional N-sulfoglucosamine sulfohydrolase (SGSH, EC:3.10.1.1)—an enzyme involved in degradation of heparan sulfate." (PMID 25807448, 2015). "Mucopolysaccharidosis type IIIA (Sanfilippo A syndrome), a fatal childhood-onset neurodegenerative disease with mild facial, visceral and skeletal abnormalities, is caused by an inherited deficiency of the enzyme N-sulfoglucosamine sulfohydrolase (SGSH; sulfamidase)." (PMID 24816101, 2014). "Mucopolysaccharidosis type IIIA (MPSIIIA), Sanflippo syndrome A, is a rare autosomal recessive LSD caused by biallelic variants in the SGSH gene, codes for the lysosomal enzyme heparan-N-sulphatase." (PMID 40855326, 2025). "Mucopolysaccharidosis type IIIA (MPS-IIIA, Sanfilippo syndrome) is a Lysosomal Storage Disease caused by cellular deficiency of N-sulfoglucosamine sulfohydrolase (SGSH)." (PMID 25807448, 2015). "Mucopolysaccharidosis type IIIA (MPS IIIA) is caused by the functional defect of N-sulfoglucosamine sulfohydrolase (SGSH; also known as sulfamidase, sulfamate sulfohydrolase and heparan N-sulfatase; EC 3.10.1.1) and represents one of the most frequent lysosomal storage diseases worldwide." (PMID 24816101, 2014). "A clinical trial of LYS-SAF302, an AAV-10 vector carrying the human N-sulfoglucosamine sulfohydrolase (SGSH) for Sanfilippo syndrome type A, was put on hold by the FDA in June 2020 following observations of localized findings on magnetic resonance imaging at the intracerebral injection sites." (PMID 33996898, 2021). "Mucopolysaccharidosis type IIIA (MPSIIIA), also known as Sanfilippo syndrome A, is a severe, progressive, neurodegenerative disorder caused by loss-of-function mutations in the N-sulfoglucosamine sulfohydrolase (SGSH) gene." (PMID 31044143, 2019). "Mucopolysaccharidosis type IIIA (MPS IIIA) is an autosomal recessive LSD due to a mutation in the gene of N-sulfoglucosamine sulfohydrolase (SGSH) that causes a lack of activity of this enzyme, involved in the degradation of the glycosaminoglycan heparan-sulfate." (PMID 33800050, 2021). "In mucopolysaccharidosis type IIIA (MPS IIIA) the exo-enzyme, N-sulfoglucosamine sulfohydrolase, is deficient resulting in an inability to hydrolyze non-reducing end glucosamine N-sulfate esters." (PMID 25513953, 2014).
Sanfilippo syndrome (7 papers, 2015 to 2024). "Herein, we study the composition and functionality of the gut microbiota of two siblings with Sanfilippo syndrome caused by the same mutation in the N-sulfoglucosamine sulfohydrolase (SGSH) gene but exhibiting differential GISs." (PMID 39201540, 2024). "MPS III, called also Sanfilippo syndrome, is caused by deficiency of the lysosomal enzyme N-sulfoglucosamine sulfohydrolase (SGSH), resulting in incomplete degradation of HS and dramatic effects on the central nervous system with devastating consequences." (PMID 31963505, 2020). "Mucopolysaccharidosis type III (MPS III, Sanfilippo disease), is a group of 4 autosomal recessive LSDs caused by pathogenic variants in SGSH, NAGLU, HGSNAT and GNS, respectively." (PMID 35646708, 2022).
lysosomal storage disease (6 papers, 2014 to 2024). A metabolic disorder caused by mutations in proteins critical for lysosomal function, including lysosomal enzymes, lysosomal integral membrane proteins, and proteins involved in the post-translational modification and trafficking of lysosomal proteins. "It would be interesting to speculate on the role of SGSH heterozygosity as a potential risk factor for neurodegeneration, as is the case for mutations in other genes involved in lysosome storage disorder, such as those in glucosaminidase (GBA) and Parkinson’s disease." (PMID 38592608, 2024). "MPS III is an autosomal recessive lysosomal storage disease caused mainly by missense variants in the NAGLU, GNS, HGSNAT, and SGSH genes." (PMID 38802532, 2024).
adenoma (1 paper, 2022). A neoplasm arising from the epithelium. "Upregulated in adenoma samples was a cluster of the proteins FCGBP, SGSH, MUC2, and PRSS8 when compared to adenomas, of which the latter two are known to play an important role in maintaining a healthy colonic epithelium." (PMID 36369736, 2022).
colorectal cancer (1 paper, 2021). A primary or metastatic malignant neoplasm that affects the colon or rectum. "N-sulfoglucosamine sulfohydrolase produces glucosamine, which is anti-inflammatory and colorectal cancer-protective." (PMID 33809624, 2021). "The on-tumor microbiota was associated with an increased abundance of enzymes involved in anti-inflammatory and colorectal cancer-protective metabolite production, including cellulose synthase and N-sulfoglucosamine sulfohydrolase, in intravenous iron-treated patients." (PMID 33809624, 2021).
Ewing sarcoma (1 paper, 2022). A small round cell tumor that lacks morphologic, immunohistochemical, and electron microscopic evidence of neuroectodermal differentiation. "Specifically, we found upregulation of enzymes involved in the catabolism of heparan sulfate proteoglycans (including SGSH, GNS, HS3ST4, HS3ST1, HS2ST1, and HS6ST1) in human Ewing sarcoma." (PMID 35285802, 2022).
GM1 gangliosidosis (1 paper, 2020). A rare lysosomal storage disorder characterized biochemically by deficient beta-galactosidase activity and clinically by a wide range of variable neurovisceral, ophthalmological and dysmorphic features. "These enzymes include α-L-iduronidase (IDUA:RTB) for MPS I - Hurler, N-sulfoglucosamine sulfohydrolase (SGSH:RTB) for MPS IIIA, and β-galactosidase (β-gal:RTB) for GM1 gangliosidosis." (PMID 32024082, 2020).
Intellectual disability (1 paper, 2020). "MPS, Type III A (OMIM # 252900) is caused by a mutation in SGSH (N-sulfoglucosamine sulfohydrolase), resulting in intellectual disability, seizures and hyperactivity." (PMID 32351971, 2020).
Sepsis (1 paper, 2022). Sepsis is defined as life-threatening organ dysfunction caused by a dysregulated host response to infection. "Any of the three and/or the pooled sepsis groups significantly differed from the ICU controls for a total of eleven genes, including higher sepsis levels for the endo-lysosomal genes DIAPH2, GUSB, HEXA, LAIR1, and SGSH." (PMID 35844509, 2022).
cancer (2 papers, 2021 to 2024). A tumor composed of atypical neoplastic, often pleomorphic cells that invade other tissues. "Increased cancer prevalence has also been reported in carriers of a potentially pathogenic variant of an LSD gene, namely CLN3, SGSH, GUSB, NEU1, and, to a lesser extent, in other genes." (PMID 39404425, 2024). "Thirty-seven significantly associated cancer–gene pairs and four genes (GBA1, SGSH, HEXA, and CLN3) with a Pan-Cancer association were identified (Pan-Cancer is a cohort of 2567 patients with cancer)." (PMID 39404425, 2024).
infection (2 papers, 2013 to 2026). The state of being infected such as from the introduction of a foreign agent such as serum, vaccine, antigenic substance or organism. "Western blot analysis in this study shows that infection with HCMV results in significant reduction in SGSH levels, and although this reduction appears to occur independently of US25-1, the result suggests targeting of this gene plays an important role in the replication of the virus." (PMID 24385903, 2013).
neurodegenerative disease (2 papers, 2014 to 2021). A disorder of the central nervous system characterized by gradual and progressive loss of neural tissue and neurologic function. "Examples of this strategy with good preclinic results have been described for MPS IIIA, a neurodegenerative disease that affects the Sulfoglucosamine Sulfamidase (SGSH) enzyme." (PMID 34944420, 2021).
tumor (2 papers, 2021 to 2025). "The on-tumor microbiota of intravenous iron-treated patients shows an increased abundance of cellulose synthase and N-sulfoglucosamine sulfohydrolase." (PMID 33809624, 2021). "Glycolipid catabolism involving proteins such as GM2A, NAGA, and SGSH is more active in patients with a low necrosis rate, which may be closely related to the energy metabolism needs of tumor cells." (PMID 40989695, 2025).
metabolic disorder (1 paper, 2014). "In an inherited metabolic disorder known as MPS IIIA the lysosomal exo-enzyme, N-sulfoglucosamine sulfohydrolase (SGSH; EC 3.10.1.1), responsible for cleaving sulfate from non-reducing end glucosamine N-sulfate (GlcNS) residues in HS is deficient." (PMID 25513953, 2014).
SGSH also shares sentences with these, for which no sentence is quoted: mucopolysaccharidosis (5 papers); psoriasis (2); retinopathy (2); cognitive decline (1); cutaneous melanoma (1); glycogen storage disease (1); hepatoma (1); Hepatosplenomegaly (1); hyperthyroidism (1); Lysosomal disease (1); mucopolysaccharidosis type 7 (1); myopia (1); Niemann-Pick disease type C (1); Onset (1); pancreatic adenocarcinoma (1); Parkinson disease (1); primary biliary cholangitis (1); Retinal dystrophies (1); rheumatoid arthritis (1); Sanfilippo syndrome type B (1); Sanfilippo syndrome type C (1); systemic lupus erythematosus (1); Usher syndrome, type 4 (1).